CDC20 (cell division cycle 20)
Diseases named in the same sentence as CDC20 in open-access papers (continued):
Sharing a sentence is not in itself a finding about the gene and the disease.
lung adenocarcinoma (19 papers, 2019 to 2025). A carcinoma that arises from the lung and is characterized by the presence of malignant glandular epithelial cells. "Due to the relatively high correlation between CDC20 and tumor stemness, and limited research on the association between CDC20 and postoperative recurrence and invasion in lung adenocarcinoma, subsequent studies primarily focused on CDC20." (PMID 39114311, 2024). "CDC20 is a positive regulator of cell division, and previous studies have shown its elevated expression in lung adenocarcinoma." (PMID 40092988, 2025). "Subsequently, the prognosis of CDC20 and its malignant clinical characteristics in lung adenocarcinoma (LUAD) patients were investigated, along with in vivo and in vitro experiments through CDC20 knockdown." (PMID 39114311, 2024). "Supporting this idea, increased CDC20 expression has been observed in lung adenocarcinoma tissues compared to normal lung tissue samples." (PMID 39795587, 2024). "CDC20 has emerged as a novel biomarker for monitoring treatment response, recurrence, and disease progression in patients with lung adenocarcinoma." (PMID 39114311, 2024). "This study identified the key gene CDC20 as a driver of lung adenocarcinoma recurrence and invasion through comprehensive bioinformatics analysis." (PMID 39114311, 2024). "The in vitro results showed that CDC20 knockdown effectively inhibited the invasion and migration of lung adenocarcinoma cells." (PMID 39114311, 2024). "Aberrant expression of Cdc20 and securin has been described in a number of cancers, including lung adenocarcinoma." (PMID 35988650, 2022). "Somatic mutation analysis showed that AURKB, CDC20, CENPF, and KNTC1 had different types of mutations in patients with lung adenocarcinoma, and the main type was missense mutation." (PMID 35354488, 2022). "TCGA database analysis did indeed show increased expression of both Cdc20 and securin in lung adenocarcinoma, as compared to control tissue." (PMID 35988650, 2022). "It is worth noting that through somatic mutation analysis, we found that AURKB, CDC20, CENPF, and KNTC1 had different frequencies of mutations in patients with lung adenocarcinoma, and mainly missense mutation type." (PMID 35354488, 2022). "CENPA combined with CDK1 and CDC20 can serve as a cluster of prognostic biomarkers for lung adenocarcinoma." (PMID 32922438, 2020). "Additionally, the colony formation assay showed decreased proliferative ability in H1299 and H1975 cells following CDC20 knockdown.In conclusion, these findings provide strong evidence supporting the crucial role of CDC20 in promoting the malignant characteristics of lung adenocarcinoma." (PMID 39114311, 2024). "Therefore, targeting the reduction of CDC20 expression by inhibiting the MAPK signaling pathway may present a potential therapeutic approach for lung adenocarcinoma." (PMID 39114311, 2024). "Furthermore, we found a close association between CDC20 and clinical pathological features, poor overall survival (OS), progression-free interval (PFI), progression-free survival (PFS), and adverse prognosis in lung adenocarcinoma patients." (PMID 39114311, 2024). "Interestingly, we determined Cdc20 expression is upregulated in human lung adenocarcinoma." (PMID 35988650, 2022). "Downregulating CDC20 expression allowed for targeted regulation of the MAPK signaling pathway, effectively inhibiting the invasion and migration abilities of lung adenocarcinoma cells." (PMID 39114311, 2024). "As a matter of fact, both CDC20 and BIRC5 were found to be co-expressed in lung adenocarcinoma, endometrial cancer, renal cell carcinoma, and thyroid carcinoma." (PMID 32043523, 2020). "Since PPP1R13L has been reported to be associated with cisplatin resistance and the IC50 decline after knocking down CDC20 was relatively small, this study explored the role of CHAF1B on cisplatin sensitivity in lung adenocarcinoma cells." (PMID 32508530, 2020).
lung adenocarcinoma (continued). "In this study, we investigated the regulatory mechanism of CHAF1B on cisplatin sensitivity in lung adenocarcinoma, because its effect on IC50 is greater than that of CDC20." (PMID 32508530, 2020). "The gene expression levels of Ki67, MCM2, CDC20, and CCND3 in tumor tissues from lent-miR-138-5p treated A549 lung adenocarcinoma tumor-bearing mice were lower than those of the other groups." (PMID 32754587, 2020).
colon cancer (15 papers, 2006 to 2025). "To validate these findings in the context of human cancer cells, we knocked down CDC20 in the human colon cancer cell line HCT116, either by siRNA or by shRNA (Fig. EV2A–D), and assessed cell survival and proliferation under SAC inhibition." (PMID 39838194, 2025). "Liu's experiments confirmed that in non‐immune environments, elevated levels of IDO1 and its metabolite Kyn in colon cancer cells significantly promote CDC20 transcription, and inhibiting IDO induces mitotic death through CDC20." (PMID 40103267, 2025). "CDC20 overexpressed in colon cancer cell lines/primary cancer tissues compared with normal colon epithelial cell lines\adjacent noncancerous tissues samples." (PMID 35800227, 2022). "CDC20 is overexpressed in a wide range of tumor types, including prostate, bladder, cervix, liver, stomach, thyroid, and colon cancer." (PMID 32596342, 2020). "CDC20 is overexpressed in oral squamous cell carcinoma, colon cancer cell lines and primary cancer tissues, compared with normal noncancerous tissue samples." (PMID 27991546, 2016). "CDC20 was overexpressed in colon cancer cell lines/primary cancer tissues compared with normal colon epithelial cell lines/adjacent noncancerous tissue samples." (PMID 23758705, 2013). "Western blotting analysis revealed elevated CDC20 expression in colon cancer cell lines (DLD1, HT29, HCT116, Lovo, SW620 and THC8307) compared with normal colon epithelial cell lines (NCM460, CCD841-coN and CCD112-coN) (upper row) (lower row)." (PMID 23758705, 2013). "In the current study, we demonstrated for the first time that CDC20 was overexpressed in colon cancer cells compared with normal colon epithelial cells." (PMID 23758705, 2013). "CDC20 overexpression was further evaluated by IHC in 244 paraffin-embedded colon cancer tissues." (PMID 23758705, 2013). "Conversely, we found that 6 genes involved in the mitotic spindle checkpoint (TTK, BUB1, BUB3, CDC20, MAD2L1, and BUB1B) are overexpressed in colon cancer specimens." (PMID 16919171, 2006). "Western blotting and immunohistochemistry were used to compare CDC20 expression in adjacent non-cancerous, cancerous and liver metastatic tissues as well as in colon cancer cell lines and normal colon epithelial cell lines." (PMID 23758705, 2013).
ovarian carcinoma (15 papers, 2018 to 2025). A malignant neoplasm originating from the surface ovarian epithelium. "An association between CDC20 overexpression and tumor grade has been reported in epithelial ovarian cancer." (PMID 39795587, 2024). "Furthermore, CDC20 overexpression has been associated with poor prognosis in breast and ovarian cancers." (PMID 39795587, 2024). "The protein expression levels of CCNA2, CCNB1, CDC20, CDCA8, CDK1, KIF11 and TOP2A were high in ovarian cancer tissues, which was further confirmed via the HPA database." (PMID 34253236, 2021). "The protein expressions of 5 hub genes (CDK1, TOP2A, CDC20, NCAPG, and MELK) are significantly up-regulated in ovarian cancer compared to normal tissues." (PMID 30453999, 2018). "This investigation highlighted CCNA2, TRIP13, CDK1, CDC20 and PRC1 as viable targets for our structure-based drug discovery campaign, as they all had a crystallised structure available in the Protein Data Bank, strong evidence of a role in ovarian cancer and known inhibitors." (PMID 39184376, 2024). "Furthermore, we confirmed that protein levels of ASF1B, CCNE1, CDC20, and RNASEH2A were significantly increased in ovarian cancer cells compared with non-transformed ovarian cells." (PMID 39199556, 2024). "However, the expression of CDC20, SDC1 and ALDH1A1 were not significantly correlated with PFS of ovarian cancer patients (all P>0.05)." (PMID 33123295, 2020).
melanoma (14 papers, 2017 to 2025). A malignant, usually aggressive tumor composed of atypical, neoplastic melanocytes. "recently also identified CDC20 as a hub gene where high expression was associated with poorer survival in melanoma." (PMID 40135438, 2025). "CDC20 (gene associated with the 8th highest-scoring hotspot) is consistently upregulated in expression between melanoma and nevi (Kunz) and the KO and WT melanoblasts (Baggiolini)." (PMID 38030698, 2023). "Overall, our analysis prioritized several recurrent functional non-coding variants that, through downregulation of CDC20, led to perturbation of key melanoma phenotypes." (PMID 38030698, 2023). "FOXM1, EXO1, KIF20A, TPX2, and CDC20 are prognosis-associated core genes of melanoma, and their high expression correlates with the low prognosis of melanoma patients and can be used as biomarkers for melanoma diagnosis, treatment, and prognosis prediction." (PMID 33912448, 2021). "The prognosis of patients with melanoma with the mentioned CDC20 promoter hotspot mutations was poorer compared with that of patients without these mutations; the differences do not reach statistical significance probably due to limited sample size." (PMID 33851100, 2021). "Survival curves showed that high expression of FOXM1,\ EXO1, KIF20A, TPX2, and CDC20 in melanoma patients with 5 of the top 10 hub genes was associated with reduced overall survival (OS)." (PMID 33912448, 2021). "Most of the CDC20 promoter hotspot mutations are identified in patients with melanoma." (PMID 33851100, 2021). "Most of the hotspot mutations in CDC20 promoter are identified in melanoma samples." (PMID 33851100, 2021). "CDC20 is also deemed as a therapeutic target, for its inhibitors show efficacy in preclinical melanoma models, including the ability to overcome BRAF inhibitor resistance." (PMID 41425556, 2025). "Pan-cancer single-cell data showed that WDR77 and CDC20 are co-expressed, which was confirmed in two melanoma-specific datasets." (PMID 41425556, 2025). "Recent reports have indicated that suppressing CDC20 in melanoma cells leads to G2/M phase arrest and inhibits cell growth." (PMID 39795587, 2024). "We also assessed how CDC20 knock-down would affect AXL expression in melanoma cell lines with relatively high levels of AXL (i.e. those classified as undifferentiated)." (PMID 38030698, 2023). "Taking expression changes between mutation status, differential gene expression of the nearest gene, and association with survival rates for those with melanoma into consideration, we specifically focus on characterizing the CDC20 promoter in melanoma." (PMID 38030698, 2023). "In all melanoma cell lines assayed, siRNA-mediated knockdown of CDC20 significantly upregulated SOX10." (PMID 38030698, 2023). "Although we did not detect metastases in the mice injected with the wild-type A375 melanoma cell line, further study is warranted to understand the metastatic potential of CDC20-high versus CDC20-low expressing melanoma cell lines." (PMID 38030698, 2023). "FOXM1, KIF20A, TPX2, CDC20, and EXO1 are hub genes of melanoma prognostic, and their high expression is strongly associated with low prognosis in melanoma patients." (PMID 33912448, 2021). "Recently, systemic delivery of Cdc20 siRNA by intraperitoneal injection was shown to inhibit B16F10 melanoma growth in tumor bearing mice and Cdc20 has been proposed as a cancer therapeutic target." (PMID 32477466, 2020). "Also, our analysis results demonstrated positive relations between WDR77 and CDC20 in melanoma before we thoroughly examined their functional relationship in melanoma progression." (PMID 41425556, 2025). "In melanoma, high CDC20 expression means aggressive disease behavior and metastatic potential." (PMID 41425556, 2025). "CDC20-low populations appear to adapt a melanocytic/proliferative gene signature, commonly seen in primary stages of melanoma, whilst CDC20-high populations may benefit migration/metastasis." (PMID 38030698, 2023).
melanoma (continued). "We therefore analyzed all melanoma cell lines in the Cancer Dependency Map cohort (DepMap) and melanoma tumors in TCGA to examine whether CDC20 expression correlates with aneuploidy." (PMID 38030698, 2023). "Taken together, these results set the precedent for a population of CDC20-low and CDC20-high cells that may drive transcriptional programs more favorable at specific stages of melanoma." (PMID 38030698, 2023). "We studied the prognosis of CDC20 mRNA expression in melanoma." (PMID 33851100, 2021). "As previously reported, CDC20 mRNA overexpression leads to significantly poorer melanoma prognosis." (PMID 33851100, 2021). "CDC20 CNV amplification also tends to result in poorer melanoma prognosis." (PMID 33851100, 2021). "Additionally, we leveraged publicly available single-cell RNA-sequencing datasets of melanoma cell lines and tumors with sufficient coverage of CDC20 for further observations of a proliferative CDC20-low transcriptional state and an invasive CDC20-high transcriptional state." (PMID 38030698, 2023). "In particular, we observed binding activity of ELF1 at the CDC20 promoter and a reduction in CDC20 upon ELF1 knockdown by siRNA in a melanoma cell line." (PMID 38030698, 2023). "Both in our CDC20 promoter indel lines and in two other melanoma cell lines that are characterized by relatively high expression of AXL, we observed a significant reduction of AXL upon CDC20 knockdown by siRNA." (PMID 38030698, 2023). "The protein expression of FOXM1, KIF20A, TPX2, CDC20, and EXO1 was higher in melanoma than in paraneoplastic tissues, consistent with our analysis results." (PMID 33912448, 2021). "Using the same method, we have also demonstrated in melanoma that cardiomyocyte-specific overexpression of CDC20 significantly inhibits DOX-induced myocardial injury, not affecting the antitumor effect of DOX." (PMID 40045239, 2025). "siRNA-mediated knockdown of ELF1 but not GABPA in A375 melanoma cells led to a significant reduction of CDC20." (PMID 38030698, 2023). "To extend these hypotheses to other melanoma cell lines, we knocked down CDC20 by siRNA and performed quantitative PCR (qPCR) on SOX10 on melanoma cell lines spanning multiple subtypes." (PMID 38030698, 2023). "ETV1, the only ETS factor with ChIP-seq data in our collation of melanoma-specific functional datasets, did not have binding activity at the CDC20 promoter in the 2 cell lines assayed (A375 and COLO-800)." (PMID 38030698, 2023). "FOXM1, KIF20A, TPX2, CDC20, and EXO1 could be used as biomarkers for melanoma diagnosis, treatment, and prognosis prediction." (PMID 33912448, 2021). "In conclusion, by combining the WGCNA analysis method with differentially expressed gene analysis, our study identified the genes FOXM1, KIF20A, TPX2, CDC20, and EXO1 highly correlated with survival melanoma patients and have the potential to serve as a prognostic biomarker in melanoma." (PMID 33912448, 2021). "However, we did not observe this up-regulation in primary melanocytes nor the non-melanoma cell line HEK 293FT, despite functional validation of the CDC20 promoter hotspot mutations in luciferase reporter assays in these cell lines." (PMID 38030698, 2023). "While these data did not include melanoma cell lines or samples due to inadequate representation of this sample type in ENCODE, we assume that transcriptional regulation will share core mechanisms across cell types due to the ubiquitous and essential function of CDC20." (PMID 38030698, 2023).
osteosarcoma (13 papers, 2014 to 2022). A usually aggressive malignant bone-forming mesenchymal neoplasm, predominantly affecting adolescents and young adults. "Overexpression of CDC20 is associated with poor prognosis in patients with osteosarcoma." (PMID 35664322, 2022). "In osteosarcoma cells, over-synthesis of CDC20 decreased the levels of p21 and Bim protein production." (PMID 36497125, 2022). "Downregulation of CDC20 inhibits the proliferation of osteosarcoma cells and induces apoptosis and cell cycle arrest." (PMID 35664322, 2022). "In a recent study, CDC20 was found to exhibit high levels of expression in osteosarcoma cisplatin-resistant cell lines, which enhanced the sensitivity of drug-resistant cell lines to cisplatin by knocking out CDC20." (PMID 33858425, 2021). "CDC20 is a gene that regulates the cell cycle, and is reported to be involved in osteosarcoma development by analyzing the gene chip data." (PMID 33858425, 2021). "It was also proved that apcin can inhibit the growth and invasion of osteosarcoma cell by targeting CDC20." (PMID 34686627, 2021). "Increased interaction between BRD7 and cdh1 or cdc20 leads to ubiquitin-mediated degradation of BRD7 in osteosarcoma." (PMID 32992509, 2020). "In this study, we found that APC/Ccdh1 and APC/Ccdc20 directly bind and degrade BRD7, a finding that is clinically relevant because a strong inverse correlation between the expression levels of BRD7 and Cdh1 or Cdc20 was observed in patients with osteosarcoma." (PMID 24840027, 2014). "Both Cdh1 and Cdc20 were mainly located in the nuclei of osteosarcoma cells, consistent with the reports showing that the tumor cells exhibited positive nuclear staining of Cdh1 or Cdc20." (PMID 24840027, 2014). "In this study, by differential gene expression we found several genes that might be the AR downstream target genes in osteosarcoma, such as cyclin G2, CDC20, Caspase-8, JNK." (PMID 28262798, 2017). "The acetylation status of Cdh1 or Cdc20 in osteosarcoma may be different from that in other cancer cell types, a topic that deserves future investigation." (PMID 24840027, 2014). "Importantly, the BRD7 protein levels are inversely correlated with Cdh1 or Cdc20 protein levels in osteosarcoma clinical samples." (PMID 24840027, 2014). "Moreover, apcin blocks osteosarcoma cell growth and invasion by reducing the level of CDC20 expression, indicating that CDC20 may represent a potential therapeutic target." (PMID 33858425, 2021). "Using the 13 gene chips, we found that six hub differentially co-expressed genes (CDK1, CCNB2, CDC20, CCNA2, BUB1, and AURKB) were highly expressed in osteosarcoma." (PMID 33858425, 2021). "In the PPI network, we selected six genes (CDK1, CCNB2, CDC20, CCNA2, BUB1, and AURKB) as the core STIL differentially co-expressed genes in osteosarcoma." (PMID 33858425, 2021). "After inhibition of CDC20, HCC cells showed a G2/M arrest, thus inhibiting tumor cells from entering mitosis and leading to osteosarcoma deterioration." (PMID 34512169, 2021). "STIL is associated with osteosarcoma proliferation and invasion, and may be promote the progression of osteosarcoma by regulating the expression of CDK1, CCNB2, CDC20, CCNA2, BUB1 and AURKB." (PMID 33858425, 2021). "In human osteosarcoma tissues, the anaphase-promoting complex/cyclosome (APC/C), a complex of E3 ligases that mediates the ubiquitination of proteins during mitosis, targets BRD7 for ubiquitin-mediated degradation through its co-activators cdh1 and cdc20." (PMID 32992509, 2020). "Moreover, BUB1–PLK1 complex mediate the phosphorylation of Cdc20 and inhibit the anaphase-promoting complex or cyclosome (APC/C) which result in the promotion of spindle checkpoint signaling in cervical cancer and osteosarcoma." (PMID 31488217, 2019).